MCM2 (minichromosome maintenance complex component 2)
Diseases named in the same sentence as MCM2 in open-access papers (continued):
Sharing a sentence is not in itself a finding about the gene and the disease.
tumor (continued). "MCM2 is a dominant MCM protein, and its upregulation was significant associated with advanced clinical stage, large tumor size, more lymph node and distant metastasis." (PMID 33936158, 2021). "Microscopic analysis of gemcitabine-treated tumor samples revealed a modest, albeit significant reduction in immunoreactivity for cell proliferation marker MCM2 as compared to vehicle-treated controls." (PMID 34868951, 2021). "Considering this, we have analyzed the expression of MCM-2 protein to evaluate the status of the proliferative capacity of tumor cells under tested conditions." (PMID 34959411, 2021). "MCM2, MCM3, MCM6, MCM8, MCM9, and MCM10 groups significantly varied and associated with the tumor stages." (PMID 34490114, 2021). "The mRNA expression of MCM2/3/4/5/6/7/8/10 in tumor tissues was significantly higher than that in normal tissues (p < 0.05), while the expression of MCM8/9/10 in tumor tissues was lower than that of other MCMs (MCM2/3/4/5/6/7)." (PMID 34404366, 2021). "Upregulated genes included several genes involved in the control of the cell cycle like E2F2, cyclin-dependent kinase 1 (CDK1) and MCM2 but also cytokine gene network with crucial effects on inflammation and tumor immunology as well." (PMID 33499054, 2021). "The gene effect scores (CERES) of MCM2-7, which reflects carcinogenic or tumor suppressor, were obtained from DepMap." (PMID 34993142, 2021). "In contrast to BP tumors, MAPKi treatment of BPN tumors led to a paradoxical increase in the percentage of MCM2-positive cells despite decreased tumor burden." (PMID 33821796, 2021). "For instance, MCM2-7 complexes contribute to the initiation of cell cycle, and are therefore potential markers for tumor screening and treatment." (PMID 32597491, 2020). "Results showed that the average of tumor growth rate of untreated mice strongly correlates to the expression level of both MCM2 and Ca9 genes (Pearson’s correlation values 0.8397 (t test 0.0002) and 0.8841 (t test 0.0001), respectively)." (PMID 33153038, 2020). "MCM2 has been reported to promote tumor proliferation by mediating DNA replication, initiation, and elongation." (PMID 33381538, 2020). "As a tumor suppressor, p27 is also reported to be able to block the G1/S transition by suppression of the MCM2 phosphorylation." (PMID 32469983, 2020). "Many clinical parameters such as advanced tumor score, advanced stage, and poor prognosis in malignancies are highly related with MCM2." (PMID 32565735, 2020). "We also measure the Mcm2 + luminal to basal ratio in pericancer tissues near and far from tumor core, and benign tissues." (PMID 32860339, 2020). "Similar results were obtained from the analysis of p-MCM2/MCM2 level between healthy samples and all tumor in CRC group (3.48-fold increment, P < 0.001), and lung group (3.56-fold increment, P < 0.00)." (PMID 32469983, 2020). "Once the nodules reached the established tumor mass threshold (2.2 cm3) the individuals were sacrificed, and the nodules analyzed by immunohistochemistry staining with mouse anti-MCM2 and mouse anti-CA9 antibodies." (PMID 33153038, 2020). "Similar to our results, a significant decrease of FTX in HCC tissues was observed, and patients with higher FTX expression exhibited longer survival, it acted as a tumor suppressor through binding with miR-374a and MCM2." (PMID 32419983, 2020). "Correlation between the expression of MCM2 and tumor size was already described, like in case of PHH3, but their connection with axillary involvement was not proved." (PMID 31446607, 2020). "Tumor HPV status in combination with pRb, CD1, MCM2, or Ki-67 has a significant association with survival, disease relapse and progression, and disease-specific death." (PMID 32058552, 2020). "From normal to tumor tissues, a shift in Mcm2 immunoreactivity from the basal to luminal cell compartment was noted by a previous study." (PMID 32860339, 2020).
tumor (continued). "We measured mice survival and tumor growth rate after xenografts of human NB treated with cisplatin in the presence of MCM2/carbonic anhydrase 9 inhibitors (ciprofloxacin and acetazolamide)." (PMID 33153038, 2020). "Our results showed that mRNA levels of MCM2, MCM6 and MCM7 were associated with certain features of tumor and the outcomes of HCC patients." (PMID 29463213, 2018). "Surprisingly, tumor samples with cytoplasmic MCM2 demonstrated excellent prognosis, showing 100% survival during the observation period of more than 200 months." (PMID 29963273, 2018). "Relative expression profiles document MCM2 drops below the tumor average significantly in UVM clusters 3 and 4 (P = 0.0001), correlating with increased malignancy and decreased disease specific survival (P = 0.0001)." (PMID 30107825, 2018). "The expression levels of JUB, HMGA2 and MCM2 were increased gradually along with the tumor differentiation grades." (PMID 29596435, 2018). "In the DNA replication pathway, the interaction of the MCM2 gene with the anti-oncomiR miR-139 was notable in the majority of tumours." (PMID 28387377, 2017). "The tumor growth curve demonstrated that the knockdown of MCM2 or MCM3 significantly inhibited tumor growth in vivo." (PMID 28460433, 2017). "The tumor volume and weight were smaller in the MCM2 and MCM3 knockdown groups than the scramble group." (PMID 28460433, 2017). "In the initial study, both MCM2 and MCM10 overexpression were significantly associated with primary tumor status in UTUC (P=0.048 and 0.004, respectively) and UBUC (P=0.005 and 0.004, respectively)." (PMID 27780919, 2016). "Optimal prognostic cut-offs for percentage expression in the tumour were 8 %, 12 and 2.33 % for Ki67, MCM2 and Geminin respectively." (PMID 26205655, 2015). "We found that a greater proportion of tumour cells showed expression of MCM2 than Ki67 and Geminin, with the latter having the lowest frequency of expression (P < 0.001; Wilcoxon signed rank test)." (PMID 26205655, 2015). "This condition would justify the conclusion that different proliferating indexes between Ki-67, MCM2, and MCM3 involve an immunoexpression pattern of proliferating tumor cells positive for Ki-67, MCM2, and MCM3." (PMID 26823641, 2015). "Our results indicate that miR-31 also suppresses tumor initiation by targeting minichromosome maintenance complex component 2 (MCM2), thus providing a check point control over initiation of DNA replication." (PMID 24970811, 2014). "Applying these MCM family expression cutoff to Kaplan-Meier survival curve estimation revealed decreased survival probability for patients with tumor expressing high levels of MCM2, MCM3 and MCM7 (p < 0.05)." (PMID 25046975, 2014). "Paraffin sections were immunostained with anti-Mcm2, and the Mcm2 proliferative index (PI) was determined as the percentage of immunoreactive tumour cell nuclei." (PMID 23618321, 2013). "The Ki67/MIB-1 and Mcm2 immunostaining revealed distinct positive tumour cell nuclei heterogeneously distributed within the tumour tissue." (PMID 23618321, 2013). "Furthermore, studies with human samples have indicated the utility of MCM2 as a proliferation marker, and a high level of MCM2 expression in malignant tumors has been associated with several clinicopathological parameters, such as advanced tumor grade, advanced stage, and poor prognosis." (PMID 22768239, 2012). "TOP2A and MCM2 immunostaining was localized to the nuclei of the tumor cells and benign mammary epithelium, while BUB1B protein immunostaining was cytoplasmic, as has been demonstrated in a variety of normal human tissues." (PMID 21785684, 2011). "Others have described the importance of pre-replication proteins, especially Mcm2, as prognostic markers in dysplasias and neoplasia at various sites in the human body." (PMID 19293805, 2009).
tumor (continued). "To determine the cell-cycle phenotype, we selected a cut point of 30% for Mcm2 protein expression to define a group (Mcm2 <30%, phenotype I) in which the majority of tumour cells reside in an out-of-cycle state." (PMID 19240714, 2009). "A higher proportion of tumour cells expressed the Mcm2 licensing factor when compared with the normal mammary epithelium, indicating a greater number of cells engaged in a cell cycle (median values: Mcm2: 92.3 vs 33.5%, P<0.001)." (PMID 19240714, 2009). "In contrast, most cancers had Mcm2 expression levels above 30% (Mcm2 >30%) in which a majority of tumour cells reside in an in-cycle state." (PMID 19240714, 2009). "Mcm2 protein expression in these tumours was significantly greater than Ki67 expression, which was itself significantly higher than geminin expression [median: Mcm2, 36.7% Ki67, 18.1% geminin, 3.4% (P<0.0001, Wilcoxon signed-rank test)]." (PMID 17406359, 2007). "Positivity for Mcm2 was defined as presence of nuclear expression of Mcm2 in greater than or equal to 40 % of tumour cells." (PMID 16368013, 2005). "In this study, patients with MCM2 expression in less than 25% of the tumour cells had a significantly better prognosis than patients with tumours with a higher MCM2 index." (PMID 16189522, 2005). "Borderline tumours of increasing grade also showed increased Mcm-2 and cyclin A expression, together with an increase in the S-phase fraction." (PMID 15083189, 2004). "The labelling index for Geminin was higher for grade III than for grade II tumours, and showed a strong positive correlation with markers of proliferation (Ki67) and DNA replication licensing (Mcm2)." (PMID 15199392, 2004). "We identify a distinct P21+/MCM2- tumor phenotype, nonproliferative and senescent-like, linked to favorable outcomes." (PMID 41990272, 2026). "Prdx2 KO improved liver weight and decreased tumor burden, tumor size, and cell proliferation, as shown at macroscopic observations and by the decreased expression of the proliferation marker minichromosome maintenance complex component 2 (MCM2)." (PMID 40932790, 2025). "The nuclear staining of MCM2, ‐4, ‐5, ‐10, and ORC1 was positive in 56.79%, 55.56%, 51.85%, 44.44%, and 50.62% of tumor tissues, respectively, and were all positively associated with tumor size, lymph node metastasis, and TNM stage (all p < 0.05)." (PMID 40548893, 2025). "Concurrently, RT-qPCR analysis revealed that the expression levels of tumor proliferation markers (MCM2 and Ki-67) and epithelial-mesenchymal transition (EMT)-related markers (CDH2, VIM, and FN1) were also significantly elevated following TRPM6 knockdown, consistent with the phenotype assay results." (PMID 41562086, 2025). "The subsequent WB results indicated that SH decreased the levels of the proliferation-promoting proteins cyclin D1 and MCM2 and increased the expression of the proliferation-inhibiting factor p21, further confirming the influence of SH on tumor cell proliferation." (PMID 41444284, 2025). "Moreover, several genes from the G2M downregulated gene set, including MKI67, MCM2, CCND1, and their STRING-interacting genes MECOM, TYMS, and MTHFR, are associated with neoplasms." (PMID 37958729, 2023). "CACYBP exerted a tumor-promoting role in CCA by suppressing ubiquitination of MCM2 and activating Wnt/β-catenin pathway, hence revealing that it may be the possible therapeutic target for CCA treatment." (PMID 37305391, 2023). "Moreover, high expression of MCM2 and CENPU was also closely associated with tumor stemness in several tumors, including GBMLGG, CHOL, STAD, PAAD, LUSC, PRAD, etc., indicating their potential as key targets for tumor treatment." (PMID 37723560, 2023). "Moreover, MCM2 was shown to be correlated with tumor progression and metastatic spreading in breast, adrenal and lung cancer." (PMID 36676734, 2023).
tumor (continued). "From the results, we noticed that tumor cells highly expressed AUP1 significantly correlated with proliferation marker (MCM2, MCM6), PI3K-AKT-MTOR pathway (Akt1, TSC1, mTOR, Foxo1), and autophagy signaling (Atg3, Atg4B, Atg4D, Atg7, Atg9A, Atg16L1) in IDH wildtype tumor cells." (PMID 37029364, 2023). "GC tumours and metastatic lymph nodes had higher MCM2 expression levels than normal tissues." (PMID 37594635, 2023). "In addition, multivariate survival analysis showed that tumor size > 5.6 cm, advanced tumor stage, ALT > 25U/L, MCM2 or NUP37 overexpression were independent risk factors for worse OS of HCC patients." (PMID 35093119, 2022). "The anti-tumour effects of Rec8 are caused by downregulation of cell growth-related genes (G6PD, SLC2A1, NOL3, MCM2, SNAI1, and SNAI2) and also by upregulation of both apoptosis or migration inhibitors (Gadd45G and LDHA) and tumour inhibitors (PinX1, IGFBP3, and ETS2)." (PMID 36139540, 2022). "This holds promise in designing anti-tumor therapeutics that specifically target MCM2." (PMID 36303105, 2022). "Targeting MCM2 with a small-molecular inhibitor showed a potent anti-tumor efficacy in NSCLC." (PMID 36303105, 2022). "We also showed a statistically significant increase in tumor (T) stage with MCM2 overexpression." (PMID 34144903, 2022). "However, in contrast to gemcitabine, UAMC-2526 did not reduce the immunoreactivity for cell proliferation marker MCM2 in tumor samples." (PMID 34868951, 2021). "The analysis of tumor masses was important to support our previous data about the activity of fendiline, since its addition to cisplatin significantly reduced the expression of Ki-67, MCM2, and GD2." (PMID 34201814, 2021). "In addition to MCM2-7 complex, other proteins in the cluster also influenced the growth and division of tumor cells by participating in the cell cycle such as RRM2, PRKAR2B, and MKI67." (PMID 33200655, 2020). "Elevated MCM2, MCM6 and MCM7 were associated with adverse tumor features and poorer outcomes." (PMID 29463213, 2018). "Furthermore, the immunohistochemistry results showed that niclosamide treatment markedly decreased the CDC34 and MCM2 positive-stained tumor cells compared to control group, which indicated that niclosamide blocked the initiation of DNA synthesis in S phase." (PMID 30687101, 2018). "Additionally, the expression trend of JUB, HMGA2 and MCM2 was increased along with the tumor differentiation grades." (PMID 29596435, 2018). "Comparison of aCGH probe log2 ratios for TLL tumor DNA and DNA from 3 clonally derived neural stem cell cultures along with the NGS data confirmed a loss of approximately half of the 45S rDNA repeats in MCM2-deficient tumors." (PMID 28915237, 2017). "The group was headed by MCM2, ECT2, and RFC4, which are associated with DNA replication, DNA repair or positive regulation of signal transduction, indicating that these genes are essential for tumor growth." (PMID 24879114, 2014). "We reviewed each grade of tumor separately and investigated whether the expression of MCM2, MCM3 and MCM7 predicts patient survival within each subgroup." (PMID 25046975, 2014). "MCM2 has been studied in a wide range of human organs, and its overexpression has been identified in various types of tumors and tumor-like lesions of the oral mucosa, larynx, stomach, colon, esophagus, breasts, lungs, ovaries, kidneys, prostate, bladder, brain and soft tissues." (PMID 24959286, 2014). "It seems, however, that the range of Mcm2 PIs varies between types of neoplasms." (PMID 23618321, 2013). "One possibility to explain the tumor spectrum in Sdl mice and Mcm2 hypomorphic mice is that the integrity of the murine Notch1 locus is sensitive to replicative dysfunction in developing T cells and that replicative stress promotes the formation of type 2 deletions at the Notch1 locus." (PMID 23133403, 2012).
tumor (continued). "Therefore, it has been proposed that a threshold level of MCM proteins (between 35 and 50% of normal for MCM2) is required for sufficient origin licensing to maintain genomic stability and prevent tumor formation." (PMID 23133403, 2012). "An understanding of the overall functions of MCM2 would enable the molecular targeting of specific functions possibly to regulate cellular proliferation/apoptosis in a cell type-specific manner and develop a novel strategy to control tumor cell growth." (PMID 22768239, 2012). "Multiparameter analysis of Mcm2–7, geminin, Aurora A, Plk1 and H3S10ph, core regulators of the G1–S and G2–M transitions, thus allows a detailed analysis of the kinetics of complex dynamic tumour cell populations." (PMID 19240714, 2009). "Recently Mcm2 has been proposed as a valuable marker for tumour evaluation." (PMID 17505513, 2007). "In summary, higher expression in MCM2 and gelsolin was significantly associated with poorer prognosis in patients with NSCLC, which suggests that higher tumor proliferation and motility may be important in the prognosis of NSCLC." (PMID 16882345, 2006). "Furthermore, the expression level in normal tissues was lower than in tumor tissues, indicating that MCM2 reflects cell proliferation." (PMID 16882345, 2006). "As part of the analysis, Mcm2/Ki67 and geminin/Ki67 ratios were also calculated for each tumour." (PMID 16278669, 2005). "46.4% of DLBCL showed positivity for Mcm2 defined as expression in ≥40% of tumour cells." (PMID 16368013, 2005). "However, only 12% of variation in NPI is explained by Mcm2, as the labelling index for this marker is approaching 100% for many of the high-grade tumours." (PMID 16278669, 2005). "However, we noted that only 12% in the variation of the NPI is explained by this marker, a consequence of Mcm2 expression reaching saturation levels in high-grade tumours." (PMID 16278669, 2005). "Mcm2 expression can be used to assess tumour proliferation and may be useful as an additional prognostic marker to refine the prediction of outcome in DLBCL." (PMID 16368013, 2005). "Mcm2 was clearly evident in the nuclei of tumour cells with low background staining." (PMID 16368013, 2005). "Moreover, we have previously demonstrated that expression of the Mcm2 origin-licensing factor rises with increasing tumour grade and other markers of proliferation in this tumour type." (PMID 15199392, 2004). "Furthermore, Yu and co-authors reported that the accumulation of SQSTM1/p62 in tumor cells in vitro was characterized by cell cycle initiation, which resulted in an increase in MCM2 expression, and enhanced proliferative ability, which is supported by our findings." (PMID 36248994, 2022). "Therefore, highly proliferative tumor cells usually exhibit high MCM2 expression levels." (PMID 31709722, 2020). "Overexpression of DHX9 could rescue MCM2 or MCM3 knockdown-induced tumor inhibition." (PMID 28460433, 2017). "The results showed that MCM2 or MCM3 knockdown could dramatically impede tumor growth in vivo." (PMID 28460433, 2017). "However, larger studies are necessary to clarify the definite role of Mcm2 in these tumours." (PMID 23618321, 2013). "The differential expression patterns of Ki67, Mcm2–7 and Geminin during the mitotic cell cycle and their tight downregulation in out-of-cycle states provide a novel and powerful multi-parameter analysis for assessment of growth fraction and cell cycle kinetics in human tissues and tumours." (PMID 15199392, 2004). "The analysis of LSIL and HSIL tissues, as well as SCC tumor samples of grades G1–3, revealed distinct expression patterns for the four proteins (TOP2A, MCM2, VCP, and p16INK4a)." (PMID 40507244, 2025). "Additionally, the study focused solely on Ki-67, and incorporating other proliferative markers (such as proliferating cell nuclear antigen as PCNA and minichromosome maintenance protein-2 as MCM-2) could provide a more comprehensive assessment of tumor behavior." (PMID 41583280, 2025).